ALB (albumin)
Diseases named in the same sentence as ALB in open-access papers (continued):
Sharing a sentence is not in itself a finding about the gene and the disease.
liver disease (continued). "In general, inflammatory cytokines reduce the level of pre-albumin synthesis by the liver, and it can also be reduced with renal and hepatic disease." (PMID 28804801, 2018). "Surgical stress, other acute stresses, hepatic disease, and renal disease decrease serum albumin levels." (PMID 28804801, 2018). "The Gage equation uses the presence or absence of liver disease, while our equation includes the lab values of AST and albumin, which can be considered a proxy for liver disease." (PMID 29861781, 2018). "The most important risk factors for HCC among all etiologies of liver disease were older age, male gender, Hispanic ethnicity, high serum AFP, alkaline phosphatase, and AST/√ALT ratio, and low platelet count and serum albumin." (PMID 30260995, 2018). "Since in the case of liver diseases the production and detoxification of albumin by the liver is strongly reduced, albumin infusion is often part of the therapy." (PMID 29364955, 2018). "Liver disorders affect the synthesis of albumin since the liver is the only site of albumin synthesis." (PMID 29805400, 2018). "For liver disease measurements, ALB is used as a marker to determine the progression, severity, decompensation, and prognosis of cirrhosis." (PMID 29789400, 2018). "For the patients with acute liver failure, entecavir was used for antiviral treatment, antibiotics were used for infection and treatment of hepatic encephalopathy, and terlipressin and albumin for hepatorenal syndrome." (PMID 28207518, 2017). "The Child-Pugh score was calculated from 5 criteria (TBIL, serum ALB, prothrombin time, ascites and hepatic encephalopathy) to indicate liver disease severity." (PMID 29180991, 2017). "Transplantation of these cells restored serum albumin level and significantly suppressed transaminase activity and liver disease." (PMID 29445403, 2017). "Albumin infusion is also indicated in patients with liver cirrhosis with AKI in the form of hepatorenal syndrome in conjunction with vasopressors." (PMID 28932401, 2017). "Transplantation of rBM-MSC-DSCs into liver-injured rats restored their serum albumin level and significantly suppressed transaminase activity as well as the morphological manifestations of liver disease." (PMID 29445403, 2017). "Bloods on day 15 demonstrated an improvement in albumin; however a persistent acute kidney injury was noted (on background of chronic renal impairment), most likely consequent to hepatorenal syndrome." (PMID 30363221, 2017). "Albumin can decrease in sheep for a variety of reasons including internal parasitism, infiltrative bowel disease or liver disease." (PMID 28441332, 2017). "Concentrations of serum albumin, ferritin, and blood clotting factors also show characteristic changes in response to liver disease stage." (PMID 26828506, 2016). "Serum albumin, which also plays a functional role as a circulating antioxidant, is often slightly elevated in heavy drinkers devoid of liver disease." (PMID 26828506, 2016). "Serum ascites albumin gradient value is weakly related to the extent of portal hypertension in patients with liver cirrhosis and its implication seems to be limited in clinics." (PMID 29201716, 2016). "This is the first study to discover changes of albumin metal ion and fatty acid binding capacities prior to conventional biomarkers for liver damage in early stage of liver diseases." (PMID 28101103, 2016). "Results showed that SSWE were negatively correlated with PLT and ALB which reflected the extent of portal hypertension and synthesis function of liver." (PMID 27511435, 2016). "In general, albumin is a good marker of liver disease severity and classically evaluates liver function." (PMID 26120587, 2015). "Given his continued decline of kidney function, triple therapy for hepatorenal syndrome (HRS) was initiated on day 3 of hospitalization including albumin human (albumin human 25%), midodrine, and octreotide." (PMID 26064715, 2015).
liver disease (continued). "On the whole, the adult age, albumin, and the initial diagnosis of the liver disease were entered into multiple Cox’s regression model; age was identified as an independent predictor for adults’ survival (HR=2.10, p<0.01)." (PMID 26306158, 2015). "Search terms included: hepatorenal syndrome; albumin; vasoconstrictor; terlipressin; midodrine; octreotide; noradrenaline; and norepinephrine." (PMID 26606982, 2015). "In the near future, it is expected that novel protein-based products, similar to albumin–paclitaxel nanoparticles (Abraxane®), will be clinically developed for use in treating a variety of hepatic diseases." (PMID 26404356, 2015). "A low serum albumin concentration due to liver disease indicates a diffuse and chronic hepatopathies, and the same nature of the disease was observed in this study." (PMID 27047120, 2015). "As a first-line therapy of type 1 HRS, both the International Ascites Club (IAC) and the American Association for the Study of Liver Diseases (AASLD) recommend a combination of vasoconstrictors and albumin infusion." (PMID 26606982, 2015). "Treatment of cirrhotic and ascitic patients with the directly vasoconstrictive drug midodrine was clearly inferior to human albumin infusion treatment in the prevention of paracentesis-induced circulatory dysfunction and hepatorenal syndrome." (PMID 25983746, 2015). "Hepatic synthetic functions; albumin and prothrombin concentration tended to decrease significantly (P = 0.0001, P<0.0001, respectively) during liver disease progression among studied groups." (PMID 26352740, 2015). "Vasoconstrictor therapy with terlipressin and concomitant albumin can improve renal function in patients with hepatorenal syndrome (HRS) type 1, but the efficacy of therapy in patients with active infection is controversial." (PMID 26722626, 2015). "A meta-analysis was performed of hepatorenal syndrome reversal and survival in relation to albumin dose." (PMID 26606982, 2015). "In our patient analysis, many patients with hepatorenal syndrome were treated very early with combined albumin and terlipressin." (PMID 25983746, 2015). "We examined the relationship between HbA1c and fructosamine values, specifically focusing on anemia (which can affect HbA1c) and albumin as a marker of liver disease." (PMID 26273478, 2015). "The results came back with albumin gradient levels 1.6 g/dL (>1.1 g/dL) suggesting portal hypertension." (PMID 26579320, 2015). "For this reason, an ‘albumin challenge’ at doses of 1 g/kg /day for at least 2 days are recommended to exclude hypovolemic renal failure and to diagnose hepatorenal syndrome (HRS)." (PMID 26178624, 2015). "At temperatures of 4, 10, 22, 33 and 37°C, we evaluated the concentration of alanine aminotransferase (ALT) as a hepatic disorder marker, and we measured albumin and bile as variables representing liver-specific physiological functions." (PMID 25900715, 2015). "GGT should be considered just as important as other LFTs in the prediction of liver disease since only albumin explained more variation in the model." (PMID 24889852, 2014). "Recent studies have shown that not only albumin concentration but also albumin function are reduced in liver disorders such as liver cirrhosis." (PMID 25369061, 2014). "Lower protein and albumin levels are frequent in patients with advanced liver disease and would lead to higher MELD scores when the Jaffé method is used to assess creatinine levels." (PMID 24587188, 2014). "The administration of human albumin in patients with hepatorenal syndrome and spontaneous bacterial peritonitis has a major impact on the prognosis of these complications." (PMID 25166619, 2014). "After adjustments for age, gender, GGT, ALB, PLT, AST and HBV DNA, elevated ALT level was positively associated with the presence of liver disease (OR=2.47, 95% CI=1.20-5.08, P=0.014)." (PMID 24260428, 2013).
liver disease (continued). "The liver disease progressed rapidly with serum bilirubin rising to 389 μmol/L, falling albumin (20 g/L (34-42 g/L), rising prothrombin time (21 seconds (normal range 10-13 seconds) and falling platelets (40 ×109/L (150-400 ×109/L)." (PMID 23679950, 2013). "For patients with mildly elevated ALT levels, results of univariate logistic regression analysis showed that GGT, ALB, PLT, elevated AST levels and HBV DNA were significantly associated with the presence of liver disease (all P≤0.044)." (PMID 24260428, 2013). "In our current study, the albumin levels were low in the three animals that died from infection compared to uninfected animals, also suggestive of liver disease." (PMID 23408990, 2013). "Increases in alanine aminotransferase (ALT), aspartate aminotransferase (AST), and sorbitol dehydrogenase (SDH), and the decrease observed in albumin are all indicative of liver disease." (PMID 23472182, 2013). "After adjustments for age, gender, GGT, ALB, PLT, ALT and AST, multivariate logistic regression analysis revealed that HBV DNA was significantly associated with the presence of liver disease (OR=0.40, 95% CI=0.21-0.77, P=0.006)." (PMID 24260428, 2013). "Between 60 and 100% of hepatitis patients showed 2 or more pathological values for parameters that indicate liver disease, namely albumin, total bilirubin, AST, ALT, and LDH." (PMID 24069490, 2013). "After adjustments for age, gender, GGT, ALB, ALT, AST and HBV DNA, multivariate logistic regression analysis revealed that PLT was significantly associated with the presence of liver disease (OR=0.99, 95% CI=0.98-1.00, P=0.007)." (PMID 24260428, 2013). "Results of univariate logistic regression analysis showed that GGT, ALB, PLT, ALT, AST and HBV DNA were all significantly associated with the presence of liver disease (all P≤0.014)." (PMID 24260428, 2013). "The serum-to-ascites albumin gradient (SAAG) accurately identifies the presence of portal hypertension and is more useful than the protein-based exudate/transudate concept." (PMID 27785191, 2012). "Patients with higher values of RDW tended to be older, were more likely to have severe liver disease, had lower levels of hemoglobin, total protein, and serum albumin, and had higher INR and total bilirubin." (PMID 22649548, 2012). "Pretreatment severity of liver disease (increased bilirubin, low albumin, prolonged PT and raised creatinine) is a more important predictor of early mortality than antiviral response in this group of patients." (PMID 21994876, 2011). "To study the hepatocyte-specific role of IKK2 mediated NF-κB activation in liver disease and cancer induced by Mdr2 deficiency, we crossed Mdr2−/− mice with mice carrying loxP-flanked IKK2 alleles and the Albumin-Cre transgene." (PMID 22022477, 2011). "These pathophysiological highly plausible mortality risk candidate biomarkers reflect disturbances in hemostasis (fibrinogen), metabolism (HbA1c), kidney disease (albumin), and liver disease (GGT)." (PMID 21749697, 2011). "Albumin dialysis using the molecular adsorbent recirculating system (MARS) is a new therapeutic approach for liver diseases." (PMID 21779339, 2011). "When comparisons of blood chemistry values was performed, euthanized animals showed increased levels of hepatic enzymes (ALP and ATL) and decrease in ALB suggestive of liver disease." (PMID 22164263, 2011). "Spontaneous bacterial peritonitis (SBP) and other spontaneous infections should be treated straight away with broad spectrum antibiotics, (e.g., cephalosporins or amoxicillin/clavulanate) and albumin to prevent the hepatorenal syndrome." (PMID 21994876, 2011). "The factors influencing mortality include the number of previous operations, a history of major infection, the site of stricture, preoperative serum albumin concentration, and the presence of liver disease and portal hypertension." (PMID 21822368, 2011).
liver disease (continued). "The serum albumin will also decrease in patients with portal hypertension because albumin is synthesized solely by hepatocytes." (PMID 21129071, 2010). "Bilirubin and albumin (the major fraction of plasma proteins) are traditionally among the biochemical parameters used to monitor the severity of liver disease." (PMID 20515488, 2010). "In the ascites fluid the polymorphonuclear count was low (PMN, <250 cells/mm3) as also the albumin (10 gr/l) and protein level (9 gr/l) with a serum-to-ascites albumin gradient (SAAG) of 2.6 pointing towards portal hypertension." (PMID 20082713, 2010). "It seems that improving BARD's diagnostic sensitivity would necessitate incorporation of the markers of subclinical portal hypertension (e.g., platelet count) and hepatic synthetic capacity (e.g., albumin)." (PMID 20584330, 2010). "Improved treatment response and renal function, shorter hospital stay and lower costs of care were reported in patients with liver disease receiving hyperoncotic albumin." (PMID 18318896, 2008). "Most patients (98%) had CP B or Albumin-Bilirubin (ALBI) grade 2-3 (100%) liver disease." (PMID 41749933, 2026). "Additionally, the association between inter-individual virome variation and proteins produced by the liver, such as albumin and coagulation factors, reflects the potential effect of liver disease severity on gut virome composition." (PMID 41438339, 2026). "Moreover, in patients with spontaneous hepatorenal syndrome, albumin replacement therapy is advised to preempt SBP and enhance prognosis." (PMID 39578719, 2025). "As expected, cirrhotic patients in the present study exhibited abnormal circulating levels of albumin, creatinine and bilirubin, and their values were linearly altered in accordance with the clinical severity of liver disease as expressed by the Child–Pugh scoring system." (PMID 39997510, 2025). "This study aims to evaluate whether the Albumin Platelet Product (APP) can serve as a reliable non-invasive fibrosis marker in patients with chronic HCV-related liver disease." (PMID 40550831, 2025). "Additionally, ALB is a key marker of nutritional status and a major prognostic factor in liver disease." (PMID 40297155, 2025). "This raises the question of whether a simpler parameter, such as the bilirubin-to-albumin (B/A) ratio, might provide a practical and clinically meaningful alternative for mortality prediction in patients with liver disease." (PMID 41428744, 2025). "The CP scoring system is widely utilized to assess the severity of liver disease on the basis of five key parameters: the presence and degree of hepatic encephalopathy, the extent of ascites, serum albumin concentration, bilirubin levels, and prothrombin time prolongation." (PMID 41573251, 2025). "On the other hand, sex (male predominance) and decreased serum ALB and PLT have also been incorporated in several LSM-based models, closely connected to genetic predisposition, life behavior, and the magnitude of portal hypertension on account of underpinning liver cirrhosis." (PMID 41184938, 2025). "Key genes such as ALB and TIMP1 emerged as central regulators of HBV-associated metabolic reprogramming and fibrosis, highlighting potential therapeutic targets for HBV-related liver disease." (PMID 40964049, 2025). "The final logistic regression model was constructed as follows: Logit (P) = −0.812 + 0.036 × (Heart Rate) −0.032 × (Systolic Blood Pressure) + 2.989 × (History of Peptic Ulcer) + 2.213 × (Presence of Liver Disease) + 0.114 × (Albumin) −0.048 × (Hemoglobin) −0.011 × (Platelet Count) + 0.122 × (CRP)." (PMID 41585275, 2025). "The strongest predictor of EM was advanced liver disease in univariate analysis, as reflected by surrogates of impaired liver function such as Child-Pugh score (CPS) B (p <0.0001), albumin-bilirubin grade 2/3 (p = 0.026, p <0.0001) or high model for end-stage liver disease score (p <0.0001)." (PMID 41635626, 2025).
liver disease (continued). "The third limitation is that mild or subclinical forms of liver disease, autoimmune disease, or hematologic disorders may indeed influence serum albumin and lymphocyte levels." (PMID 41373357, 2025). "In 385 cirrhotic portal hypertension patients, low FT3 correlates with higher Child-Pugh/MELD scores, lower hemoglobin/albumin, and poorer 2-year survival; FT3 negatively associates with disease severity scores; FT3 and prothrombin time are independent prognostic factors." (PMID 41585788, 2025). "The analysis identified a history of peptic ulcer, hemoglobin (Hb), platelet count (PLT), albumin (ALB), heart rate, systolic blood pressure (SBP), liver disease, and CRP as significant independent risk factors for 1-year rebleeding in patients with acute upper gastrointestinal bleeding." (PMID 41585275, 2025). "Moreover, this study clearly demonstrates the significant impact of serum ALB levels on TEIC pharmacokinetics in patients with liver disease." (PMID 41424785, 2025). "Liver disease severity can be assessed through various parameters, such as albumin, bilirubin and prothrombin time and multiple scores have been used for that purpose, including the Child-Pugh score, Model for End-stage Liver Disease (MELD) with its variations and Albumin-Bilirubin (ALBI) score." (PMID 40948746, 2025). "An underlying hepatic disease and Reye syndrome were also ruled out based on normal serum albumin, bilirubin, coagulation parameters and liver enzymes." (PMID 39915375, 2025). "Low levels of serum albumin can be signs of kidney or liver disease." (PMID 39205155, 2024). "Albumin infusion is primarily used for plasma replacement and rehydration in critically ill patients, as well as treating hepatic diseases such as ascites, spontaneous bacterial peritonitis, hepatorenal syndrome, and post-perforation syndrome." (PMID 38500655, 2024). "However, on multivariate analysis, only age, respiratory rate, fibrinogen, WBC, PT, PTT, ALB, MI, liver disease, MST, APS III, MV and norepinephrine were identified as independent factors." (PMID 39568443, 2024). "Moreover, when combined with splanchnic vasoconstrictors, albumin effectively improves kidney function in patients with hepatorenal syndrome (HRS)." (PMID 39434907, 2024). "LSWV combined with ALB and PT exhibited a high predictive effectiveness for the assessment of hepatic functional reserve, assisting the clinical diagnosis and management of liver diseases." (PMID 38549933, 2024). "Hepatorenal syndrome Terlipressine was more effective than albumin only." (PMID 39286706, 2024). "Of note, we have excluded patients with preexisting liver disease that may affect the production of albumin as well as lactate clearance." (PMID 39272772, 2024). "Normally, the lowering of albumin level indicates a liver disease." (PMID 38741871, 2024). "Hepatic failure leads to features of decompensated liver disease, like ascites due to low albumin production, defective coagulation due to the inability of the liver to make coagulation proteins, and portal vein thrombosis caused by direct invasion of the vessels by tumor." (PMID 39149633, 2024). "It was described that albumin concentrations were reduced during liver disease." (PMID 38900819, 2024). "A low level of serum albumin is an indicator of liver disease." (PMID 39070451, 2024). "Besides the liver enzymes, albumin, globulin and the ratio of these two, play an active role in liver disease recovery." (PMID 38737864, 2024). "Published data on the effects of SB on the serum levels of ALT, AST, GGT, ALP, bilirubin, albumin, glucose, insulin, cholesterol, triglycerides, biomarkers of systemic inflammation, oxidative stress, and bacterial translocation in various liver disorders were systematized." (PMID 39203520, 2024). "Moreover, the concentrations of TBIL, ALB, and TP are also used as important markers for liver diseases." (PMID 39728765, 2024).